NPHP3 (nephrocystin 3)
Description:
Required for normal ciliary development and function. Inhibits disheveled-1-induced canonical Wnt-signaling activity and may also play a role in the control of non-canonical Wnt signaling which regulates planar cell polarity. Probably acts as a molecular switch between different Wnt signaling pathways. Required for proper convergent extension cell movements.
Synonyms: KIAA2000; NPH3; FLJ30691; FLJ36696; MKS7; SLSN3; CFAP31; RHPD; RHPD1
Tractability: Small molecule: a structure with a bound ligand is known. Antibody: its Gene Ontology location is reachable by antibodies, with medium confidence. PROTAC: ubiquitination databases record sites on it.
Gene: Protein-coding gene on chromosome 3 (132,680,609 to 132,722,432, reverse strand). Ensembl gene ENSG00000113971.
Subcellular location: Cell projection, cilium
Subcellular location (Human Protein Atlas): Nucleoli; Primary cilium; Cytosol; Nucleoplasm; Primary cilium tip; Vesicles
Pathways (Reactome):
Organelle biogenesis and maintenance: Trafficking of myristoylated proteins to the cilium
Gene Ontology:
Molecular function: protein binding
Biological process: atrial septum development; convergent extension involved in gastrulation; determination of intestine left/right asymmetry; determination of left/right symmetry; determination of liver left/right asymmetry; determination of pancreatic left/right asymmetry; determination of stomach left/right asymmetry; heart looping; kidney development; kidney morphogenesis; lung development; maintenance of animal organ identity; negative regulation of canonical Wnt signaling pathway; photoreceptor cell maintenance; regulation of Wnt signaling pathway, planar cell polarity pathway; ureter development; cilium assembly; convergent extension; epithelial cilium movement involved in determination of left/right asymmetry
Cellular component: ciliary tip; cilium; ciliary base; ciliary inversin compartment; cytosol; extracellular region
Genetic constraint (gnomAD): Loss-of-function variants: 87 observed, 119.13 expected, observed/expected ratio (o/e) 0.73, 90% interval 0.61 to 0.87. The upper end of that interval is the gene's LOEUF score, 0.87, which puts it in group 3 of 6, group 1 being the genes least tolerant of losing a copy. Missense variants: 1,202 observed, 1,291.9 expected, observed/expected ratio (o/e) 0.93, 90% interval 0.89 to 0.98. Synonymous variants: 461 observed, 486.15 expected, observed/expected ratio (o/e) 0.95, 90% interval 0.88 to 1.02.
Gene-disease validity (ClinGen):
ClinGen rates the evidence that NPHP3 causes each of these diseases.
nephronophthisis (autosomal recessive): Definitive. Progressive tubulointerstitial injury, inherited in an autosomal recessive pattern, caused by mutations in genes involved in ciliary function, which may result in an end stage renal failure.
Homologues: Orthologues: chimpanzee NPHP3 (99% identical), macaque NPHP3 (99% identical), dog NPHP3 (95% identical), pig NPHP3 (95% identical), mouse Nphp3 (89% identical), rat Nphp3 (88% identical), guinea pig NPHP3 (88% identical), rabbit NPHP3 (86% identical), tropical clawed frog nphp3 (77% identical), zebrafish nphp3 (69% identical). Paralogues in human: KLC1 (14% identical), KLC4 (14% identical), KLC2 (13% identical), KLC3 (12% identical), APPBP2 (8% identical).
Diseases named in the same sentence as NPHP3 in open-access papers:
NPHP3 is named in the same sentence as 52 diseases in open-access papers, as found by Europe PMC text mining. Sharing a sentence is not in itself a finding about the gene and the disease. The quoted sentences say what the papers report.
nephronophthisis (12 papers, 2018 to 2026). "Patients with nephronophthisis caused by nephrocystin 3 (NPHP3) variants rapidly progress to end-stage kidney disease." (PMID 41898549, 2026). "Ocular involvement in nephronophthisis (NPHP) caused by NPHP3 mutations is common, including nystagmus, retinitis pigmentosa, oculomotor nerve disorders, and leber congenital amaurosis, etc.." (PMID 39076169, 2024). "In patients with syndromic nephronophthisis caused by several genes (including NPHP3, IQCB1, CEP290, and MKS1), an additional heterozygous variant in RPGRIP1L is associated with retinitis pigmentosa." (PMID 37628633, 2023). "Since this initial report, NPHP3 mutations have been associated with a wider spectrum of disease, including infantile nephronophthisis (resulting in end-stage renal failure before 5 years of age38) and Meckel syndrome." (PMID 30269812, 2018). "Common variants are associated with elevated creatine in association studies;In patients with syndromic nephronophthisis caused by several genes (including NPHP3, IQCB1, CEP290, and MKS1), an additional heterozygous variant in RPGRIP1L is associated with retinitis pigmentosa." (PMID 37628633, 2023). "Nephrocystin-3 (NPHP3), identified as a protein associated with nephronophthisis, a genetic ciliopathy, was reported to be localized at the Inv compartment, a distinct proximal segment of the ciliary body." (PMID 35946311, 2022). "The significance of synonymous variants in PKD1 and NPHP3, underlying ADPKD and nephronophthisis, respectively, has recently been described." (PMID 33059616, 2020). "Nephronophthisis 3 (NPHP3) is localized in the inversin compartment of PC." (PMID 39408701, 2024). "In this case, sequencing and MLPA analysis of NPHP1 was also performed, together with the sequence analysis of other rarer genes related to nephronophthisis (INVS, NPHP3, NPHP4, IQCB1): no pathogenic variant was found in these genes." (PMID 37372410, 2023).
ciliopathy (11 papers, 2012 to 2026). A genetic disorder of the cellular cilia or the cilia anchoring structures, the basal bodies, or of ciliary function. "NPHP3 is responsible for the ciliopathies caused by ciliary dysfunction such as autosomal recessive kidney disorder, the most frequent genetic disease of renal failure in children and young adults." (PMID 39408701, 2024). "In Family 1, targeted exon capture and sequencing of a ciliopathy panel of 121 genes, as previously reported, identified a variant predicted to affect function in NPHP3 (NM_153240.3, c.3003del; p.(Phe1001Leufs*61)) in combination with a synonymous SNV (c.2154C>T; p.Phe718=)." (PMID 30002499, 2018). "Here, we report a male newborn with severe NPHP3-related ciliopathy with a severe RHPD1 phenotype and a novel genotype that was confirmed by using whole-exome sequencing (WES) and Sanger sequencing verification." (PMID 36253741, 2022). "We also found the most common pathogenic genes, NPHP1 and NPHP3, which were carried by 52% of Chinese children with NPHP-related ciliopathies." (PMID 36939782, 2021). "NPHP3, a ciliary protein, is responsible for various ciliopathies." (PMID 39408701, 2024). "Additional heterozygous (non-pathogenic) alleles in known ciliopathy genes were also detected including NPHP3: rs772079066 and DNAH1: rs536088715." (PMID 28973549, 2017). "Some ciliopathies are caused by mutations in genes that are primarily associated with non-ciliopathy syndromes (for example, TRIM32/BBS11, NPHP3, and KIF7)." (PMID 23351659, 2012). "These genes are specifically associated with pathology in certain organs; for example, NPHP3 is associated with renal–hepatic–pancreatic dysplasia, BBS11/TRIM32 causes limb girdle muscular dystrophy, and KIF7 causes acrocallosal syndrome – none of these is considered a ciliopathy." (PMID 23351659, 2012).
cystic kidney disease (5 papers, 2009 to 2026). A congenital or acquired kidney disorder characterized by the presence of renal cysts. "Interestingly, the pcy mouse, a spontaneously occurring renal cystic disease model that closely resembles NPH, harbors a homozygous missense mutation in the mouse NPHP3 ortholog (Nphp3) that most likely causes the kidney phenotype." (PMID 18607645, 2009). "This approach was first shown to markedly reduce renal cyst formation and fibrosis and limit disease progression in a polycystic kidney rat model of ARPKD (PCK) and the pcy/Nphp3 mouse model." (PMID 34055783, 2021). "A class of bioactive lipid metabolites called cyclooxygenase (COX) oxylipins (e.g., prostaglandins, leukotrienes) has been shown to be elevated in diseased kidneys of rodent models of NPH (pcy/Nphp3 and jck/Nek8/Nphp9 mice and Han:SPRD-Cy/Anks6/Nphp16 rats) and other cystic kidney diseases." (PMID 34055783, 2021).
Hepatic fibrosis (4 papers, 2009 to 2025). The presence of excessive fibrous connective tissue in the liver. "Four of six children with NPHP3 mutations were diagnosed with Boichis syndrome due to liver fibrosis." (PMID 36227438, 2023). "Mutations in NPHP3 were described in families with renal disease alone, as well as in families with renal disease associated with hepatic fibrosis or retinal degeneration." (PMID 18607645, 2009). "Mutations of the NPHP3 gene were reported in affected members with hepatic fibrosis and NPH from one family." (PMID 18607645, 2009). "Two patients with variants in NPHP3 had mild liver fibrosis." (PMID 40247009, 2025). "Homozygous NPHP1 possibly modified by heterozygous NPHP4 with early-onset ESKD;Compound heterozygous NPHP3 modified by heterozygous NPHP4 variant with early-onset ESKD and hepatic fibrosis;TTC21B contributes possible modifier alleles to NPHP4." (PMID 37628633, 2023). "Previous studies reported that NPHP3 loss-of-function mutations could cause rapid worsening of liver fibrosis, but they did not indicate the cause of the rapid worsening." (PMID 36227438, 2023).
Nephropathy (4 papers, 2009 to 2025). A nonspecific term referring to disease or damage of the kidneys. "NPHP3 is implicated in nephropathy involving significant yet nonspecific pathologies, with occasional extra-renal system involvement." (PMID 40909434, 2025).
cystic kidneys (3 papers, 2016 to 2021). "Mouse models of InvsC defects (Invs, pcy/Nphp3, jck/Nek8/Nphp9 and Anks6/Nphp16-mutated mice) show enlarged cystic kidneys characteristic of infantile NPH, although pcy/Nphp3 and Anks6/Nphp16 mice have slow disease progression and (late stage) tubulointerstitial fibrosis." (PMID 34055783, 2021). "Although reported initially as a cause of adolescent NPHP, variants that affect function in NPHP3 are a prominent cause of infantile NPHP and may present antenatally with enlarged cystic kidneys and sometimes cause the perinatally lethal Meckel Syndrome." (PMID 30002499, 2018). "The function of this compartment is poorly understood, but human or mouse mutations in genes encoding components of the INVS compartment, INVS/NPHP2, NPHP3 and ANKS6/NPHP16, are known to lead to infantile nephronophthisis with cystic kidneys, congenital heart defects and laterality defects." (PMID 26967905, 2016). "Indeed, mutations in genes encoding other components of the INVS compartment (INVS/NPHP2, NPHP3 and ANKS6/NPHP16) are known to lead to infantile NPH associated with enlarged cystic kidneys or to kidney cystic dysplasia associated with congenital heart defects and situs inversus." (PMID 26967905, 2016).
Meckel syndrome (3 papers, 2012 to 2018). "The collecting ducts of the wpk rodent model for Meckel-Gruber syndrome, and NPHP3 mice, all display longer cilia." (PMID 22899815, 2012). "The remaining genes, such as GLYCTK, DRD5, NPHP3, and FANCI, were well-characterized pathogenic genes for some other rare diseases with recessive mode of inheritance or multi-gene diseases, such as D-glyceric aciduria, attention deficit-hyperactivity disorder, Meckel syndrome, and Fanconi Anemia." (PMID 30693022, 2018).
cervical cancer (2 papers, 2019 to 2024). A primary or metastatic malignant neoplasm involving the cervix. "In conclusion, although many questions remain about the mechanisms underlying Tβ4 action, our results provide a novel evidence to the effect of Tβ4 expression on ciliogenesis through the regulation of NPHP3 in HeLa cervical cancer cells." (PMID 31048733, 2019). "Based on the physical interaction of Tβ4 and NPHP3 in Y2H screening assay, we examined whether Tβ4 expression is involved in primary cilia formation in HeLa cervical cancer cells." (PMID 31048733, 2019). "Here, we investigated whether Tβ4 regulates ciliogenesis and whether Tβ4 and NPHP3 cooperate in primary cilia formation in HeLa cervical cancer cells." (PMID 31048733, 2019). "In conclusion, while further studies are needed to define the mechanisms underlying AATF action, our results provide novel evidence of the effect of AATF on ciliogenesis and VBL resistance through the regulation of NPHP3 and IFT88 expression in HeLa cervical cancer cells." (PMID 39408701, 2024).
Fabry disease (2 papers, 2021 to 2024). Fabry disease (FD) is a progressive, inherited, multisystemic lysosomal storage disease characterized by specific neurological, cutaneous, renal, cardiovascular, cochleo-vestibular and cerebrovascular manifestations. "Genetic findings that modified the diagnosis in 19 patients included mutations in patients with NPHP (NPHP1 [n = 4], TTC21B [n = 3], ANKS6 [n = 1], NPHP3 [n = 1], NPHP4 [n = 1]), collagenopathies (COL4A5 [n = 7], COL4A3 [n = 1]), and Fabry disease (GLA [n = 1])." (PMID 39363361, 2024).
Joubert syndrome (2 papers, 2022 to 2024). Joubert syndrome (JS) is characterized by congenital malformation of the brainstem and agenesis or hypoplasia of the cerebellar vermis leading to an abnormal respiratory pattern, nystagmus, hypotonia, ataxia, and delay in achieving motor milestones. "The sucrose shock-specific program also included two Meckel/Joubert syndrome genes (B9D1 in cluster 2 and NPHP3 in cluster 4)." (PMID 35924891, 2022).
kidney failure (2 papers, 2022 to 2023). An acute or chronic condition that is characterized by the inability of the kidneys to adequately filter the blood. "Chinese children with NPHP have a relatively high frequency of NPHP3 mutations, which are characterized by rapid progression to kidney failure and liver involvement." (PMID 36227438, 2023). "NPHP3, one of the ciliary proteins, contributes to the most frequent genetic disease of renal failure." (PMID 36498831, 2022). "Mutations in NPHP3 are responsible for adolescent nephronophthisis (NPHP), which is an autosomal recessive poly cystic kidney disorder and the most frequent genetic disease of renal failure in children and young adults." (PMID 36498831, 2022).
lung carcinoma (2 papers, 2020 to 2022). "Among the downregulated and hypermethylated genes associated with both RMST and DIRC3 (including BNIPL, HORMAD2, and NPHP3), HORMAD2 is the only gene related to lung cancer." (PMID 35356464, 2022).
retinal degeneration (2 papers, 2020 to 2022). Degeneration of the retina. "Of note, mutations in the Nphp3 gene are associated with Senior–Løken Syndrome 3 (SLS3) characterized by retinal degeneration and vision loss." (PMID 35806143, 2022).
retinitis pigmentosa (2 papers, 2023 to 2024). Retinitis pigmentosa (RP) is an inherited retinal dystrophy leading to progressive loss of the photoreceptors and retinal pigment epithelium and resulting in blindness usually after several decades. "In patients with a variety of syndromic ciliopathies attributed to variants in NPHP3, IQCB1, CEP290, and MKS1, a common RPGRIP1L variant (p.Arg229Thr) (present in over 8% of South Asians and 3% of other populations) is significantly enriched in patients who also have retinitis pigmentosa." (PMID 37628633, 2023).
situs inversus (2 papers, 2011 to 2016). A congenital condition in which there is complete right-to-left reversal of the position of the major thoracic and abdominal organs (that is, they are arranged in a mirror image of the normal positioning). "The authors demonstrated in patients and mice that NPHP3/Nphp3 mutations produce several clinical manifestations such as situs inversus, polydactyly, central nervous system anomalies, congenital heart disease, preau-ricular fistulas, and several renal malformations including MCDK." (PMID 21689023, 2011).
breast carcinoma (1 paper, 2014). "Among the 69 ciliary-associated genes analyzed, seven genes showed a statistically significant decrease in expression in breast cancers (log fold change: DYNC2H1 = -0.66; IFT46 = -1.07; PKD2 = -1.67; NPHP3 = -1.10; BBS2 = -1.51; BBS4 = -0.78; TTC8 = -1.46)." (PMID 24987519, 2014).
Caroli disease (1 paper, 2014). Caroli disease (CD) is a rare congenital liver disease characterized by non-obstructive cystic dilatations of the intra-hepatic and rarely extra-hepatic bile ducts. "Comparing the WES findings with the different phenotypes of the twins, we determined whether any variants in genes related to Caroli disease, hepatic function, or kidney function could act as a genetic modifier for Caroli disease (such as NPHP3, PKD1 and so on)." (PMID 24710345, 2014).
cone dystrophy (1 paper, 2024). An inherited ocular disorder characterized by the loss of cone cells, the photoreceptors responsible for both central and color vision. "Patient one had a clinical diagnosis of cone dystrophy, and the Invitae kit reported VUS in ARHGEF18, INPP5E, NPHP3, and SEMA4A; BG reported VUS in ARHGEF18 and SEMA4A." (PMID 38892829, 2024).
congenital heart disease (1 paper, 2011). A heart disease that is present at birth. "A group from Germany published the study of a homozygous Nphp3 -deficient animal model to determine the role of nephrocystin-3 during early development and left-right body asymmetry, heterotaxia, congenital heart disease, and embryonic lethality." (PMID 21689023, 2011).
developmental delays (1 paper, 2016). "A 0.4-Mb heterozygous loss in 3q22.1, which includes UBA5 and NPHP3, was previously detected in a patient with global developmental delays, impaired hearing, muscular hyptonia, and seizures." (PMID 26872069, 2016).
hepatocellular carcinoma (1 paper, 2023). A malignant tumor that arises from hepatocytes. "In cancer, TOLLIP has been described to promote hepatocellular carcinoma via the PI3K/AKT pathway, and NPHP3 has been shown to regulate cancer cell viability by mediating the primary cilium formation." (PMID 37947626, 2023).
Hypertension (1 paper, 2021). The presence of chronic increased pressure in the systemic arterial system. "For example, in a patient with NPHP3-related infantile NPH isosorbide dinitrate was used to treat hypertension by restoring nitric oxide generation." (PMID 34055783, 2021).
Kidney Cyst (1 paper, 2023). Abnormal fluid filled sac within the kidney, either acquired or congenital. "In mouse, Anks6, Invs, Nphp3, and Nek8 mutants develop kidney cysts, while mutants of several other NPHP genes show no obvious kidney phenotypes." (PMID 36920028, 2023).
nephromegaly (1 paper, 2025). "Given its status as a potential second most prevalent NPHP gene in China and a major cause of infantile NPHP, NPHP3 should be prioritized in pediatric cases exhibiting low-molecular-weight proteinuria with nephromegaly." (PMID 41399018, 2025).
polycystic kidney (1 paper, 2025). "In this study, we observed that the ultrasound phenotypes of a fetus with HNF1B mutation included hyperechoic kidney and polycystic kidney, whereas the ultrasound phenotypes of the fetus with NPHP3 and KMT2D gene mutations included hyperechoic kidney and abnormal nervous system structure." (PMID 40909434, 2025).
renal coloboma syndrome (1 paper, 2021). Renal coloboma syndrome (RCS) is a genetic condition characterized by optic nerve dysplasia and renal hypodysplasia. "Out of the 12 families of ESRDu, we detected the biallelic variants of NPHP3 in one family and the heterogeneous variant in PAX2 in the second family confirming the diagnosis of renal coloboma syndrome." (PMID 34215756, 2021).
renal fibrosis (1 paper, 2026). A final common manifestation of a wide variety of chronic kidney diseases characterized by glomerulosclerosis and tubulointerstitial fibrosis. "In the context of renal fibrosis phenotype ontology (RENAL_FIBROSIS), upregulation was observed in ANTXR1, MUC1, SLC37A4, and NPHP4, while ARL3 and NPHP3 were significantly downregulated." (PMID 41573374, 2026).